CHEK2 (checkpoint kinase 2)
Diseases named in the same sentence as CHEK2 in open-access papers (continued):
Sharing a sentence is not in itself a finding about the gene and the disease.
breast cancer (continued). "Moreover, 914 breast cancer patients (8.3%) carried a CHEK2 mutation (659 missense mutations and 255 protein-truncating mutations (47 1100delC; 91 IVS2 + 1G/A and 117 del5395 mutations) and 502 breast cancer patients (4.6%) carried a BRCA1 mutation." (PMID 35205705, 2022). "In addition, two patients harbored a PV in a PDAC-predisposition and another gene: ATM/FANCE (PDAC patient with colon cancer) and BRCA2/CHEK2 (early-onset breast cancer PDAC patient)." (PMID 34503238, 2021). "In a single institutional review of 1185 breast cancer cases using multi-gene panel testing (MGPT), a high occurrence of bilateral tumors was observed in 26.3% of the ATM germline variant carriers and in as much as 41.2% of CHEK2 variant carriers." (PMID 35008774, 2021). "Considering segregation of PALB2 PGVs and CHEK2_1100delC within a family, we detected perfect concordance for PALB2 in FDR with breast cancer but not for CHEK2 with only 7/13 testing positive for the familial variant." (PMID 34113003, 2021). "The fact that the model also can be applied to CHEK2:c.1100delC carriers is supported by a study of low-risk breast cancer variants in 34 000 women with and without a family history of breast cancer." (PMID 34285278, 2021). "Variants of unknown/uncertain significance (VUS) in breast cancer susceptibility genes BRCA2, CHEK2 and BRIP1 were also identified in three different PABC patients (15%)." (PMID 34011307, 2021). "They suggested that the following words be added: autosomal dominant inheritance, HER 2 positive, mammography, MRI, physician assistant, preventive examination, specialized nurse, receptor, sentinel lymph node, triple negative tumor, other breast cancer genes (like CHEK2, PALPB2, and ATM)." (PMID 33001269, 2021). "Our data highlight the need for guideline-adherent choices, based on the evidence that CHEK2 carriers are at moderate risk for breast cancer and no risk for ovarian cancer, while underscore the possible role of chemoprevention with tamoxifen." (PMID 33925588, 2021). "Additionally, the difference in the recommendations from the UKCGG/UKGTN meeting and the TD have resulted in further variation in practice, particularly for the moderate risk breast cancer predisposition genes ATM and CHEK2." (PMID 33568439, 2021). "Most interestingly, our data highlight the need for guideline-adherent choices, based on the evidence that CHEK2 carriers face a moderately increased risk for breast cancer and no elevated risk for ovarian cancer." (PMID 33925588, 2021). "There have been no formal estimates of age-specific cumulative risk of breast cancer for all CHEK2 pathogenic (including likely pathogenic) variants combined." (PMID 33803639, 2021). "The estimated breast cancer HR for carriers of pathogenic CHEK2 variants was 4.9 (95% CI 2.5–9.5; p < 0.0001), meaning that carriers are estimated to have breast cancer incidences that are 4.9 times those for non-carriers." (PMID 33803639, 2021). "Thereby, heterozygous CHEK2 gene germline mutations have been observed in patients with the Li-Fraumeni cancer-predisposition syndrome (LFS), with other cancers such as breast cancer, colon cancer, thyroid cancer, bladder cancer, ovarian cancer, gastric cancer, renal cancer, and prostate cancer." (PMID 34630562, 2021).
breast cancer (continued). "A two-fold risk for breast cancer in carriers of CHEK2 mutations compared with noncarriers has been reported with a lifetime risk of breast cancer of approximately 15% to 20%." (PMID 35127508, 2021). "We next determined the power of the competing RVAS tests to identify the 8 breast cancer risk genes (BRCA1-Missense, BRCA1-LoF, BRCA2-Missense, BRCA2-LoF, PALB2, BRIP1, CHEK2 and BARD1) at the three TIER levels 5%, 0.1% and 0.01% and at three levels of VE of 2%, 1% and 0.5% (Iberian: S6 Fig)." (PMID 33606672, 2021). "The increased prevalence of breast cancer, breast cancer at age 50 or younger, and second primary breast cancer was also observed when the comparisons were restricted to monoallelic and homozygous carriers of CHEK2 c.1100del." (PMID 31993860, 2020). "While the elevated PRS distribution followed the breast cancer incidence distribution with highest rates in the early-settlement region in South-Western Finland, the allele frequencies for the PALB2 and CHEK2 mutations were highest in the late-settlement region in Eastern Finland." (PMID 33318493, 2020). "A panel NGS analysis involving 8085 Chinese breast cancer patients revealed only 18 (0.3%) carriers of pathogenic CHEK2 mutations; eight of them carried the novel founder nonsense mutation c.C417A (p.Y139*)." (PMID 33322746, 2020). "It is important to establish if women who are homozygous for CHEK2 c.1100del or are biallelic carriers of any CHEK2 PV have higher breast cancer risks than monoallelic carriers, since this could impact management recommendations." (PMID 31993860, 2020). "Therefore, ORs were determined separately for the breast cancer types for which there were sufficient numbers in both biallelic and monoallelic CHEK2 PV carriers: ductal invasive and DCIS." (PMID 31993860, 2020). "Additionally, pathogenic alterations in PALB2, ATM, CHEK2, and NBN are correlated with an increased risk for breast cancer and/or other cancers, whereas other genes such as BRIP1, RAD51C, and RAD51D are associated with an increased ovarian cancer risk." (PMID 32733558, 2020). "Representative examples of such genes include those encoding lipoprotein lipase (LPL), where variants increase risk of coronary artery disease via perturbation of triglyceride metabolism, and checkpoint kinase 2 (CHEK2), which increases risk of breast cancer via perturbation of DNA repair pathways." (PMID 32820175, 2020). "For both PALB2 and CHEK2, a high PRS further increased the breast cancer risk." (PMID 33318493, 2020). "A combination of breast cancer PRS in the top decile and a mutation in the CHEK2 variant increased the lifetime risk to 59% – a risk comparable to that seen in PALB2 mutation carriers – whereas those with a PRS in the bottom decile had a risk similar to the population level." (PMID 33318493, 2020). "It has been suggested that CHEK2 carriers may be more sensitive to ionizing radiation that may contribute to contralateral breast cancer rates in patients receiving adjuvant radiotherapy following breast conserving surgery." (PMID 31935898, 2020).
breast cancer (continued). "CHEK2 is identified in the CGC from frameshift germline mutations (i.e. not somatic missense mutations) and annotated as a tumour suppressor whereby frameshifts variants lead to increased risk of familial breast cancer." (PMID 30670742, 2019). "These include CHEK2 mutations in breast cancers and also in a variety of other cancers including thyroid cancer, EWSR1 in Ewing sarcoma, RET in hereditary medullary thyroid carcinoma, NRP1 in breast cancer and germline POT1 variants in malignant melanoma." (PMID 31614935, 2019). "One study of over 94,000 women with breast cancer and 75,000 controls found that women in the highest 1% of a 313 SNV PRS had a lifetime risk of 32.6%, well above that of PVs in genes such as ATM and CHEK2." (PMID 30832243, 2019). "Remarkably, two out of four families reported multiple cases of second primary or bilateral breast cancers (PRI-177 III-2 and III-3; PRI-193 III-1 and IV-1), consistent with published meta-analysis reporting the association of CHEK2 with second primary breast cancers." (PMID 31780696, 2019). "Furthermore, variants of CHEK2 (1100delC, IVS2 + 1G/A, del5395bp, and I157T), PALB2 (509_510delGA and 172_175delTTGT) and RECQL (c.1667_1667 + 3delAGTA) are also associated with breast cancer in the Polish population." (PMID 29678143, 2018). "We also identified CHEK2 c.1111C > T variants in 2.5% (3/120) of Korean breast cancer patients without BRCA1/2 mutations." (PMID 29338689, 2018). "Finally, among the breast cancer predisposition genes with moderate/high-penetrance, seven genes (BMPR1A, PTEN, CDH1, NF1, RAD51C, BRIP1, and CHEK2) were replicated for Korean BRCAX (eight for Asian and 15 genes for European high-risk breast cancers)." (PMID 30323354, 2018). "For the moderate-risk homologous recombination repair (HRR) breast cancer genes ATM, BARD1, CHEK2, and NBN, 3.3% (p = 7.2 × 10− 04) of unselected pancreatic cancer cases carried a clearly pathogenic variant, and weighted inclusion of HiP-VUS increased the proportion to 5.1% (p = 2.3 × 10− 08)." (PMID 29945567, 2018). "Three hundred and fifty-six women had a CHEK2 mutation, 370 women had a first-degree relative with breast cancer (and no CHEK2 mutation) and 2269 women had neither risk factor." (PMID 28265306, 2017). "As a result, we concluded that it is not a suitable predictive test for other CHEK2 mutations in a clinical setting for breast cancer among Iranian population." (PMID 28680382, 2017). "Moreover, many large-scale studies are needed to confirm our results, particularly in patients with different ethnic origins for better understanding of CHEK2 1100delC, IVS2 + 1G > A, del5395bp, and I157T mutations and susceptibility to breast cancer." (PMID 28680382, 2017). "CHEK2 and NBN are also known breast cancer associated genes that were found to each have an interesting variant of unknown significance in our sample." (PMID 28591191, 2017). "Here we have genotyped the CHEK2 mutations I157T and c.1100delC, the FANCM mutation p.Q1701X, the PALB2 mutation c.1592delT, the RAD51C mutations c.837+1G>A and c.93delG, and the RAD51D mutation c.576+1G>A in 68 male breast cancer patients." (PMID 28874143, 2017). "All three associations with breast cancer risk reported for CHEK2 variants remained statistically significant after adjusting for the other tests conducted in relation to breast cancer risk, but not after correcting for all tests for all cancers." (PMID 27595995, 2016).
breast cancer (continued). "In this study, we screened the mutations on the entire coding sequence of the CHEK2 gene by direct sequencing on a cohort of Asian high-risk breast cancer patients who have been tested negative for BRCA1 and BRCA2 gene mutations." (PMID 25629968, 2015). "The observed focal amplifications of the ERBB2 genomic region and the increase in gene expression levels of the genes herein suggest that a proportion of CHEK2*1100delC breast cancers could be related to the ERBB2/Her2Neu intrinsic subtype." (PMID 26553136, 2015). "In this study, the entire coding sequence of the CHEK2 gene was screened for mutation on a total of 59 breast cancer patients who were non-BRCA carriers from UKM, HKL and HPJ using direct DNA sequencing." (PMID 25629968, 2015). "Interestingly, a small region of (focal) copy number gain on chromosome 17 (including the ERBB2 locus) is found in almost half (6/14) of the CHEK2*1100delC breast cancers." (PMID 26553136, 2015). "This could in part result from the small number of CHEK2*1100delC breast cancer samples used in this study." (PMID 26553136, 2015). "Also, hierarchical clustering showed a great degree of heterogeneity of copy number profiles amongst the CHEK2*1100delC breast cancers, while BRCA1-mutated breast cancers frequently co-cluster in hierarchical cluster analysis." (PMID 26553136, 2015). "For example, a splice-site mutation in CHEK2 IVS2 + G > A has been found to be associated with breast cancer susceptibility in Poland, and the S428F allele of the CHEK2 gene increases breast cancer risk in Ashkenazi Jewish women." (PMID 25674498, 2015). "In addition, mutations in the CHEK2, ATM and BRIP1 genes confer a moderate lifetime risk of breast cancer but are rare and account for less than 5 % of familial breast cancer cases." (PMID 26553136, 2015). "Unsupervised hierarchical clustering of copy number profiles of all luminal CHEK2*1100delC and BRCAX samples, i.e. including samples with high TILs, suggests a great degree of heterogeneity amongst the CHEK2*1100delC breast cancers comparable to that seen in the BRCAX breast cancers." (PMID 26553136, 2015). "The current study is the first study performing mutation analyses in BRCA1, BRCA2 and PALB2 and determining the frequency of CHEK2 c.1100delC in triple negative and/or premenopausal breast cancer patients in South Africa through both next generation sequencing and large rearrangement testing." (PMID 26577449, 2015). "We screened the entire coding region of CHEK2 gene on 59 high-risk breast cancer patients who tested negative for BRCA1/2 germline mutations from UKM Medical Centre (UKMMC), Hospital Kuala Lumpur (HKL) and Hospital Putrajaya (HPJ)." (PMID 25629968, 2015). "This variant has been previously reported in several other CHEK2 studies and is likely to be a neutral polymorphism with no elevated risk of breast cancer." (PMID 25629968, 2015). "No CHEK2 1100delC mutations were detected in any of 134 individuals, including 59 women diagnosed with breast cancer at an early age (<40 years), 10 women with bilateral breast cancer, and 6 women with ovarian cancer." (PMID 25674498, 2015). "We performed copy number and gene expression profiling to investigate whether CHEK2*1100delC breast cancers harbor characteristic genomic aberrations, as seen for BRCA1 mutated breast cancers." (PMID 26553136, 2015). "The CHEK2-associated breast cancer risk of 20–30% lifetime is not generally high enough to warrant consideration of risk-reducing bilateral mastectomy, but heightened surveillance with additional annual breast MRI is recommended." (PMID 26484312, 2015). "Few characteristic CNAs for CHEK2*1100delC breast cancers were found." (PMID 26553136, 2015).
breast cancer (continued). "However, 14 BRCAX and three CHEK2*1100delC samples of the luminal breast cancers were also found to have such high mRNA signature values and were not used in supervised class comparison of CNAs and differential gene expression analysis." (PMID 26553136, 2015). "A similar effect of such rare CHEK2 variants has been reported for colorectal and breast cancer, supporting the importance of less frequent alterations in not-commonly analyzed CHEK2 regions." (PMID 26506619, 2015). "In a previous study of our group regarding distant disease-free survival and breast cancer-specific survival of primary BC, no differential effect of adjuvant chemotherapy or endocrine therapy was observed in CHEK2 1100delC compared with non-CHEK2 breast cancer patients." (PMID 25958056, 2015). "On the basis of these studies, we believe that the CHEK2 1100delC mutation is either rare or absent in high-risk breast cancer groups in China." (PMID 23318652, 2013). "The incidence of this mutation in breast cancer is very low; therefore, CHEK2 1100delC is not an appropriate indicator in breast cancer gene mutation screening." (PMID 23318652, 2013). "2/3 (67%) CHEK2 mutation carriers as compared to 8/104 (8%) non-carriers progressed on neoadjuvant epirubicin monotherapy for locally advanced breast cancer." (PMID 21819606, 2011). "Previous studies have shown that some CHEK2 missense substitutions are pathogenic, but the scale of their contribution to breast cancer susceptibility relative to that of T+SJVs is not known." (PMID 21244692, 2011). "Although previous studies have identified a group of high penetrance susceptibility genes and loci of breast cancer, such as BRCA1, BRCA2, and CHEK2, these genes could only explain a small part of the genetic risk of breast cancer." (PMID 21912531, 2011). "Breast cancer patients with CHEK2 1100delC have been found to have a poorer disease-free and overall survival, and this may partly be due to a disadvantageous response to treatment that causes DNA damage." (PMID 21542898, 2011). "Furthermore, breast cancer in Russia and some neighboring countries is caused not only by mutations in BRCA genes, but also by heterozygous inactivation of the CHEK2 and NBS1." (PMID 19338682, 2009). "Yet the CHEK2 gene does not appear among the top SNPs in the largest most recent breast cancer association study." (PMID 19956539, 2009). "BRCA2 is the first CHEK2-modifying gene proposed for breast cancer; however, the relevant BRCA2 allele (T1915M) was rare and was present in only 6% of the population controls and in 11% of the cases of CHEK2-associated breast cancer." (PMID 19401704, 2009). "Subsequent population-based studies have shown that a recurrent loss of function CHEK2 mutant, CHEK21100delC is present in approximately 1% of the population and in 5% of familial breast cancer families lacking a BRCA1 or BRCA2 mutation." (PMID 18797466, 2008). "The novel CHEK2 missense variant identified in this study, R406H, is unlikely to contribute to breast cancer risk in French Canadian women." (PMID 18706089, 2008). "Nonetheless, the potential modulation by CHEK2 of both BRCA1 and BRCA2 would point to an important function for this checkpoint kinase in the DNA damage repair pathways implicated in the development of breast cancer." (PMID 18797466, 2008).